CCND1 (cyclin D1)
Diseases named in the same sentence as CCND1 in open-access papers (continued):
Sharing a sentence is not in itself a finding about the gene and the disease.
tumor (continued). "The activation of the PI3K/AKT signaling pathway can regulate its downstream transcription factors NF-κB, β-catenin, cyclin D1 and c-Myc to promote the proliferation of tumor cells." (PMID 36003306, 2022). "A large number of studies have found that drugs can inhibit the growth of tumor cells by suppressing the expression of cyclins such as CCND1 and CDK4." (PMID 36364084, 2022). "From the results of the tumor markers analysis, cyclin-D1, MDA and AKT results of MTX-MNMs were nearly the same as those of PIP-pNMs/MTX-MNMs." (PMID 36559161, 2022). "We observed that tumors explanted from R26AKT1E17K; MMTV-Cre mice presented increased levels of pAKT1 at S473 and pGSK at S9/22 in comparison with the corresponding normal mammary gland; tumor tissues also exhibited elevated levels of cyclin D1." (PMID 35681625, 2022). "Cyclin-D1 is an important cell cycle regulator and plays an important role as an oncoprotein in tumor proliferation." (PMID 36292101, 2022). "Cyclin D1 expression has also been investigated in various human tumors and found to be overexpressed in several tumor types." (PMID 36136690, 2022). "The tumor suppressor effect of miR-124 was also observed through the inhibition of cell cycle-related cyclin D1, cyclin-dependent kinase 2 (CDK2), cyclin-dependent kinase 4 (CDK4), and cyclin-dependent kinase 6 (CDK6)." (PMID 35326471, 2022). "The Cyclin D1 expression rate showed positive correlations with the tumor size, depth of infiltration, lymph node metastasis, and pTNM stage of the ESCC (P < 0.05)." (PMID 36072972, 2022). "Cyclin D1, a cell cycle protein, is a major downstream effector molecule of Wnt signaling that regulates the tumor cell cycle as well as proliferation." (PMID 35653786, 2022). "We then detected the protein levels of SH3TC2 and two cell-cycle regulators, CDK4 and Cyclin D1, in the tumor tissues from nude mice by Western blot and found that knockdown of SH3TC2 caused a decrease in CDK4 and Cyclin D1." (PMID 36568637, 2022). "As a tumor suppressor, miR-211 inhibits cell proliferation and induces cell apoptosis by down-regulating cyclin D1 and CDK6 in OC to block cells in G0/G1 phase 36." (PMID 35912006, 2022). "Cyclin D1 regulates the cell cycle, and activation of Cyclin D1 induces abnormal proliferation of tumor cells." (PMID 35711625, 2022). "As our experiment showed, the studied compound induced a significant downregulation of cyclin D1 and its phosphorylated form in both tumor cell lines (MBA-MB-231 and MCF-7) during the whole exposure period (from 24 to 72 h)." (PMID 35335879, 2022). "Previous studies have also found that ZC3H13 inhibits the Ras-ERK signaling pathway, reduces the expression of Snail, Cyclin D1, and Cyclin E1, and upregulates the expression of occludin and Zo-1, thereby inhibiting tumor progression." (PMID 38024481, 2022). "In assessing the effect of AOM/DSS on cell proliferation, Ki67, PCNA, BrdU, and Cyclin D1 expression was identified in the colonic crypt cells and tumor epithelia by immunofluorescence staining." (PMID 35269806, 2022). "Specifically, CCND1 amplified tumor tissues exhibited decreased mRNA expression of CD8, Gzm, B2m and Tap1 and significantly lower proportions of CD8 T cell and T follicular helper cells." (PMID 35844619, 2022). "STAT1 has been shown to regulate cell cycle progression by modulating the expression of cyclin D1 in tumour cells." (PMID 35781872, 2022).
tumor (continued). "We found mean CCND1 CN ≥ 4 < 6 in 45 cases (8.6%), and mean CN ≥ 6 in 42 cases (8.0%)., In tumours with CN increase, CN increase was observed in most tumour cells." (PMID 35459982, 2022). "As transcription factors, FOXM1 can regulate downstream cell cycle-related genes, including PLK, cyclin B1, cyclin D1, and Cdk2, to promote cell proliferation and tumor progression." (PMID 36585925, 2022). "In ACP, positive cells are widely distributed in each layer including palisade epithelial cells, stellate cells, and “whirl-shaped” cell clusters; in PCP, cyclin D1-positive cells are also evenly distributed in the epithelial cells of the tumor." (PMID 35707464, 2022). "The mechanism of anti-tumor effects involves inhibition of telomerase activity and cell cycle arrest in the G0/G1 phase, down-regulation of nuclear factor kappa-B and cyclin D1 and enhanced NK cell-mediated cytotoxicity." (PMID 35093182, 2022). "The implication of cyclin D1 in the DNA repair pathway and its activity in tumor maintenance leading to tumor development have been reported." (PMID 36072388, 2022). "In animal experiments, we confirmed that the changes in the expression levels of PUMA, Bax, Bcl-2, p21, Cyclin D1 and P-p65 in tumor tissues were consistent with those observed in vitro." (PMID 35759135, 2022). "Conversely, cells cultured on low stiffness ECM have decreased cell cycle entry and cyclin D1 expression, and the softening of tissues inhibits tumor development." (PMID 36229487, 2022). "Nuclear PTEN also exhibits its tumor-suppressive effect through G1-phase cell-cycle arrest by preventing cyclin D1 localization and decreasing the level of cyclin D1, together with the effects of PTEN on p27Kip1, to suppress the cell cycle." (PMID 35954330, 2022). "Previous studies have shown that immunohistochemical analysis is superior to routine H&E assessment and it is recommended to use at least three immunohistochemical markers such as synaptophysin, chromogranin, PGP 9.5 and cyclin-D1 to demonstrate tumor tissue." (PMID 34558657, 2022). "Quantitative analysis of COX2, iNOS, and cyclin D1 expression from multiple frames of acquired images showed significantly higher expression in normal mucosa (p<0.05) as well as in tumor area (p<0.05) compared to both control and γ exposed mice." (PMID 36584137, 2022). "Consistent with the whole transcriptome sequencing data that showed overexpression of CCND1 transcripts in MCL tumor tissues, we observed markedly higher expression of CCND1 mRNA based on qRT-PCR." (PMID 36359790, 2022). "Staining for vimentin and cyclin D1 was seen within tumor cells at the front of invasion in 100 and 84.4% of the tumors, respectively." (PMID 34495397, 2022). "Wnt/β-catenin signaling-related targets, such as c-myc and cyclin D1, are critical contributors to tumour cell proliferation potential." (PMID 35999582, 2022). "CPE-shRNA loaded exosomes can inhibit malignant tumor cell proliferation via Cyclin D1 and c-MYC suppression." (PMID 35328535, 2022). "A possible mechanism is that p21Cip1 and p27Kip1 abolished cyclin D1 nucleocytoplasmic shuttling, a process involved in promoting abnormal cell survival, tumor progression and drug resistance." (PMID 35934718, 2022). "The Western blot analysis showed that fucoidan treatment downregulated the expression of β-catenin and its downstream target genes, c-Myc, Cyclin D1 and Survivin, in 4T1 and tumor-bearing mice." (PMID 36079579, 2022). "Future studies are needed to determine if the E2F1-dependent induction of SREBP1 contributes to the expression of cyclin D1 and the inhibition of Rb in tumor cells." (PMID 36091143, 2022). "In contrast, the in-silico drug candidate identification of scAmpi marked the complete tumor population to be potentially sensitive to palbociclib treatment, based on the over-expression of CCND1 and further supported by the expression of CDK4." (PMID 35658001, 2022).
tumor (continued). "Nuclear translocation results in β-catenin acquiring tumor-promoting properties by activating the expression of various oncogenes such as fibronectin, cyclin D1, or c-myc, leading to deregulation of cell-cycle progression." (PMID 35215208, 2022). "While NFκB activation generates an inflammatory microenvironment that favors tumor growth, mTOR activation increases the translation of cell survival genes (cyclin D1, Bcl-xL, and COX2)." (PMID 35900274, 2022). "YTHDF1 deficiency regulates the transformation efficiency of cyclin-dependent kinase 2 (CDK2), cyclin-dependent kinase 4 (CDK4), and cyclin D1 (CCND1) through the Keap1-Nrf2-AKR1C1 pathway to inhibit tumour cell proliferation and xenograft tumorigenesis." (PMID 35518355, 2022). "A Western blot analysis demonstrated that cynaroside inhibited β-catenin and cyclin D1 (an active marker of the β-catenin signaling pathway) in tumor cells." (PMID 35954428, 2022). "The combination of LY2874455 and abemaciclib was necessary to completely inhibit the growth of tumor harbored FGF3/4/19/CCND1 amplification." (PMID 35814257, 2022). "Cell cycle-related genes, including CCND1, CDK4, CDKN2A, and RB1, were frequently mutated in MSCs, PCs, and tumor cells." (PMID 35087207, 2022). "The addition of mTOR inhibitor to palbociclib markedly reduced p-Rb (P = 0.017) and cyclin D1 (P < 0.001) levels in these S6K1-overexpressed tumours." (PMID 36042494, 2022). "The expression levels of proteins associated with the cell cycle (CDK4, CDK6 and cyclin D1), proliferation (Ki67 and PCNA) and the pathway (GSK-3β, p-GSK-3β, β-catenin) in tumor tissue samples were determined using western blotting." (PMID 34719320, 2022). "Ki67 and cyclin D1 expression was downregulated in tumor tissue, while p16, p21, p-IRE1α, and LC3B expression was upregulated." (PMID 36010550, 2022). "Cyclin D1 enhances cell migration and invasion activity in fibroblasts by regulating RhoA as well as tumor cells." (PMID 35945910, 2022). "Consistently, intermittent hypoxia treatment significantly promoted tumor cell proliferation, as assessed by Cyclin D1 staining." (PMID 35805134, 2022). "As an E3 ubiquitin ligase of cyclin D1, Fbxo4 regulates cell cycle progression in both normal and tumor cells." (PMID 35565262, 2022). "The main oncogenic effect of cyclin D1/CCND1 upregulation or gene amplification is to promote tumor cell proliferation." (PMID 36210843, 2022). "MiR-9 suppresses the expression of cyclin D1 and Ets1 by binding to their 3′-UTRs; it has been seen that it leads to the inhibition of proliferation, invasion, and metastasis processes in tumor cells." (PMID 36551878, 2022). "Overexpression of CCND1, an oncogene, contributes to poor prognosis and tumor recurrence, leading to the etiology of HCC." (PMID 35628212, 2022). "For the genetic analysis with the Oncomine Focus Panel, amplification of CCND1 was found in the primary and recurrent tumor of #16." (PMID 36555474, 2022). "In view of the positive correlation between c-Myc and CCND1, it was demonstrated that tumor-inhibiting effects of CDC42EP3 knockdown also lose efficacy upon overexpressing c-Myc." (PMID 35365622, 2022). "We found that the anti‐Chi3L1 antibody inhibited MMP9 and cyclin D1 expression compared with the vehicle‐treated tumor tissues." (PMID 34861103, 2022). "Upregulation of the levels of CCND1 transcripts was observed at relapse while the nodal tumor load was significantly lower." (PMID 36467789, 2022). "Simvastatin treatment significantly inhibited transcript levels of LRP6 (1.69‐fold), AXIN2 (3.33‐fold) and Cyclin D1 (1.59‐fold), while we found a higher expression of the tumour suppressor APC levels compared to control." (PMID 35118811, 2022).
tumor (continued). "While the variation of cyclin D1 expression was high between tumors within every tumor group, six out of 15 CxPAs showed moderate or high nuclear cyclin D1 expression." (PMID 35637257, 2022). "Reduce tumor growth and inhibited the activation of NF-κB pathway and expression of their proteins (cyclin D1, COX-2, MMP (mitochondrial membrane potential)-2, MMP-9, and Bc1-xL) that involve in proliferation, metastasis, and anti-apoptosis of tumor cells." (PMID 36670910, 2022). "The proportion of cases with histopathological grade 3 tumours was higher among cases with mean CCND1 CN ≥ 6, compared to cases with mean CN < 4 (50% vs. 29%, p = 0.007)." (PMID 35459982, 2022). "Some researchers have pointed out that tumor inhibition can be achieved by inhibiting Cyclin D1 expression." (PMID 36072972, 2022). "The overexpression of TIM3 in breast cancer induces the upregulation of various factors, including VEGF, TWIST, MMP1, c-Myc, and Cyclin D1, which promote tumor proliferation, tubal formation, invasion, migration, and tight junction deterioration." (PMID 36358792, 2022). "In the present study, we demonstrated that RASAL2 was an oncogene in PCa that promoted PCa cell proliferation and tumour growth through the PI3K/AKT/cyclin D1 signalling pathway." (PMID 35668070, 2022). "Further, qPCR analysis of normal appearing colonic mucosa and tumor samples showed that the expression of β-catenin and NF-κB downstream gene targets (Ptges2, Nos2, and Ccnd1) were greater in 28Si exposed mice relative to control and γ radiation groups." (PMID 36584137, 2022). "Cyclin D1 levels must be high during G1 phase for a cell to begin DNA synthesis, but then must be reduced to low levels during S phase to allow for efficient DNA synthesis, however, an aberrant cyclin D1 activity is observed in tumor cells." (PMID 35444536, 2022). "The vast majority of cases demonstrated pronounced cyclin D1 staining at the front of invasion while vimentin staining was seen exclusively in tumor cells at the invasion front." (PMID 34495397, 2022). "β-catenin regulates various downstream targets including cyclin D1 and c-Myc to promote tumor progression." (PMID 35780119, 2022). "Similar to TERT promoter GA frequencies, CCND1 amplification was most frequently detected in the penSCC (15%) and vulSCC (18%) tumor." (PMID 35881043, 2022). "In hepatocellular carcinoma, miR-1269a/FOXO1 can up-regulate Cyclin D1, thereby promoting tumor cell proliferation." (PMID 35252180, 2022). "IHC assay also indicated that hsa_circ_0000277 induced inhibitory effects on SOX4, β-catenin, c-myc and cyclin D1 protein levels in tumor tissues." (PMID 35241028, 2022). "In the future, more efforts should be devoted to outline the mechanisms of CCND1 as a tumor oncogene in cancers." (PMID 35246017, 2022). "The PC mice had abundant tumours, markedly elevated proliferation markers (survivin/CCND1) and PI3K/Akt/mTOR, and reduced p21/PTEN/cytochrome C/caspase-3 and apoptosis." (PMID 35326689, 2022). "It is reported that cyclin D1 played a critical role in cell cycle control and tumor development, and downregulation of cyclin D1 induced cell cycle arrest at the G1 phase." (PMID 36467091, 2022). "All tumor groups showed both nuclear and cytoplasmic expression of cyclin D1, and the expression varied between tumors within the same group." (PMID 35637257, 2022). "This borderline tumor also shows a strong reaction with cyclin-D1, which can be used as an additional marker for the confirmation of the diagnosis." (PMID 36292216, 2022). "The anti-tumor effects of A3AR activation involves multiple signaling pathways including NF-κB and Wnt signaling pathways leading to inhibition of cell growth regulatory genes, such as c-myc and cyclin D1, and apoptosis of tumor cells." (PMID 35093182, 2022).
tumor (continued). "Alteration of both the CCND1 gene and Cyclin D1 protein are frequently found in precancerous lesions and neoplasms." (PMID 35626215, 2022). "There is increasing evidence that cyclin D1 is often dysregulated and serves as a biomarker of tumor phenotype and disease progression." (PMID 35707464, 2022). "Analysis of archived tumor samples using validated IHC assays, confirmed that both Rb and cyclin D1 were expressed in all patients in the MTD cohort." (PMID 36970055, 2022). "This evidence indicated that NBT inhibited xenograft tumor development in vivo by suppressing p-GSK3β/β-catenin/Cyclin D1 signaling." (PMID 36263164, 2022). "The anti-proliferative effect of Met has been shown in several tumor cell lines and endothelial cells due to cyclin D1 down-regulation." (PMID 35656067, 2022). "In the cancer pathway, cell-cycle gene cyclin A1 and cyclin D1 were upregulated, while tumor proliferation and metastasis pathway FAK-PI3K and Ras-PI3K were upregulated; DNA damage repair-related gene RAD51 was also upregulated." (PMID 36090994, 2022). "The present results show that mice receiving either supplemental FO/Se or an EGFR inhibitor have significantly lower expression of Ki67 and the cell-cycle marker proteins cyclin D1/E than untreated tumor-bearing mice." (PMID 36547898, 2022). "According to the reports, in addition to promoting tumor migration, invasion, and metastasis, S100P also enhances cell proliferation by up-regulating cyclin D1 and CDK225 and confers chemoresistance by binding and inactivating p5326,27." (PMID 35013450, 2022). "Rhein treatment also downregulated p-mTOR, p-p70S6K, HSF1, and cyclin D1 in tumor tissues, which further confirmed that rhein suppressed CRC cell growth by inhibiting the mTOR signaling pathway." (PMID 33946531, 2021). "Abnormal activation of Wnt signaling pathway can boost tumorigenesis and tumor progression through activating target genes like c-myc, cyclin D1, etc.." (PMID 34704918, 2021). "Candesartan significantly decreased the expression of cyclin D1 and survivin suggesting the mechanism by which candesartan can inhibit tumor cell proliferation." (PMID 34121975, 2021). "Collectively, all these results reveal that circPSMA1 functions as a tumor promoter through the circPSMA1/miR-637/Akt1-β-catenin (cyclin D1) regulatory axis, which can facilitate the tumorigenesis, metastasis, and immunosuppression of TNBC." (PMID 33911067, 2021). "Regarding EMPD, a recent report suggested that CDK4 and cyclin D1 are overexpressed in EMPD tumor cells." (PMID 34395284, 2021). "More importantly, the anti-tumor effects of bortezomib targeting cyclin D1 and Hippo/YAP will need to be evaluated in vivo in KIT-independent GISTs." (PMID 34025442, 2021). "The CDK4/6 inhibitor, rafoxanide, decreases total and phosphorylated CDK4/6, cyclin D1, and pRB thus suppressing the G1/S transition and reducing cSCC tumor volume in mice." (PMID 34553848, 2021). "We reported the G0/G1 growth phase cycle arrest of tumor cells induced by licorice is related to the down-regulation of CDK4-Cyclin D1 complex, which subsequently led to an increased protein abundance of PD-L1." (PMID 34641869, 2021). "This function of PLEKHA7 suppressed expression of pro-tumor promoting proteins, including Cyclin D1, Snail, and c-Myc, and inhibited AIG." (PMID 33525380, 2021). "Homeobox A1 (HOXA1), an oncogene motivating tumor growth and tumor motility by regulating the expression of downstream pro-migration and pro-invasion genes, cyclin D1 (CCND1), MET, smoothened (SMO), and semaphorin 3C (SEMA3C)." (PMID 33917233, 2021). "Candesartan suppressed tumor cell proliferation and migration by modulating Cyclin D1, MMP3/9, and E-cadherin." (PMID 34121975, 2021). "Many genetic alterations can affect the functional activities of oncogenes or tumor suppressors, including alterations in cyclin E, cyclin D1, and p27." (PMID 33920506, 2021).